EGF (epidermal growth factor)
Diseases named in the same sentence as EGF in open-access papers (continued):
Sharing a sentence is not in itself a finding about the gene and the disease.
tumor (continued). "CAFs are activated by tumor cells through the secretion of factors such as TGF-β, PDGF, EGF, CTGF, and FGF, or in response to damage-associated molecular patterns (DAMPs) released by damaged tissue or necrotic tumor cells." (PMID 34572771, 2021). "In murine models, depletion of macrophages/microglia has led to a reduction in tumor growth and in line with this, some factors released by GAMs such as IL-6, IL-1β, EGF, STI-1 and TGF- β can promote tumor growth." (PMID 33802571, 2021). "M2 TAMs secrete pro-tumor factors (IL-4, IL-6, IL-10, IL-13, EGF, and VEGF), while tumor suppressor M1 TAMs express antitumor factors (IL-12, major histocompatibility complex (MHC) class II, and TNF-α)." (PMID 34341329, 2021). "Both catechin nanoemulsion at 20 mg/kg BW and paclitaxel at 10 mg/kg BW were the most effective in reducing tumor volume and weight in mice through a decline in both EGF and VEGF levels in serum." (PMID 34071530, 2021). "For example, the proliferation of tumor cells is promoted by growth factors such as EGF, PDGF, HGF, and bFGF, which are secreted by macrophages." (PMID 34639167, 2021). "Tumor hypoxic microenvironment has been shown to provoke the activation of angiogenesis factors such as VEGF/EGF/TGF-β, CSCs and EMT, and drug resistance in a variety of tumor types." (PMID 33805447, 2021). "Contrary to tumor cells, the presence of erlotinib in EGF-incubated fibroblasts in 3D not only induced the degradation of the receptor but prevented it (lanes 5–8), as happened in 2D cultures." (PMID 34572731, 2021). "The balance of the two components, PEG and EGF, was shown to be fundamental, while confirming ICONs as a promising platform for siRNA smart delivery into tumours." (PMID 33808586, 2021). "A milestone was achieved by Simpson groups, who recently revealed that tumours can be classified based on EGF endocytosis profile from an ex vivo EGF endocytosis assay to predict antibody-based anti-EGFR therapy efficacy." (PMID 34831480, 2021). "It is also evident that EGF (Epidermal growth factor) or ErbB-mediated signaling has a major role in the proliferation of tumor cells." (PMID 34202265, 2021). "TAM (M2) produce tumor growth and invasive factors such as growth factors (EGF and VEGF), cytokines, enzymes supporting the process of angiogenesis (MMP9), inhibit the expression of anti-cancer factors such as IL-12 and accumulate at hypoxic sites." (PMID 34526531, 2021). "Even though TAMs exhibit either polarization phenotype, they are considered as M2-like phenotype-acquired macrophages and produce epidermal growth factor (EGF) and MMPs to accelerate the migration and angiogenesis of tumor in TME." (PMID 33748122, 2021). "Tumor progression.Cell migration.Cell invasion.Metastasis.TGF-β-induced EMT.Tumor immune evasion.EGF-mediated cellular growth." (PMID 34070747, 2021). "Either epidermal growth factor (EGF)-based or tumor endothelium-based targeting have been employed to study the time dependence of the active targeting." (PMID 33578756, 2021). "Macrophages promote breast cancer tumor growth by secreting various growth factors including EGF, which is recognized by tumor EGF receptors to stimulate tumor cell proliferation and migration." (PMID 35936112, 2021). "Prolonged inflammation leads to loss of MHC I expression on tumor cells and can be attributed to the effect of an immunosuppressive cytokine TGF-β, IL-10, and the epidermal growth factor (EGF) which are secreted in the TME." (PMID 34858978, 2021). "Proliferation medium is serum-free and supplemented with β-FGF and EGF which allows propagation of multipotent, self-renewing tumour-spheres (NS)." (PMID 33894774, 2021). "We used tumour-like substrate stiffening and oncogenic EGF stimulation to modulate the amplitudes of mechanical BM stresses to potentiate the invasive transition of non-malignant cells." (PMID 33921304, 2021).
tumor (continued). "Primary, metastatic or recurrent tumours were enzymatically digested and grown in Matrigel using a medium containing Rspondin-1, Noggin, EGF, FGF2 and 10, nicotinamide, PGE2 and inhibitors of TGF-β and p38 MAPK signalling." (PMID 33580825, 2021). "From our results and other studies, it seems that EGF predominantly plays a role in tumour progression in the early phases, when the tumour is smaller and before lymph nodes are affected." (PMID 34115785, 2021). "In the Hif1α signaling pathway, TME-derived growth factors IGF and EGF are likely promoting HCC-tumor derived ARNT, which is in turn promoting the expression of known pro-angiogenesis genes PAI1, and TGFA." (PMID 33995488, 2021). "Depletion of PDK1 impeded EGF-enhanced binding of HNSCC cells to endothelial cells as well as the metastatic seeding of tumor cells in lungs." (PMID 33739396, 2021). "Once recruited to the tumour site and activated via CSF-1R, pro-tumourigenic GAMs secrete epidermal growth factor (EGF) to stimulate tumour cell invasion." (PMID 33803414, 2021). "For instance, EGF maintains pluripotency in neuroglioma stem cells, whereas bFGF is critical for the formation of tumour spheres." (PMID 34208001, 2021). "The establishment of the critical role of the EGF-ERK-SOX9-TSPAN8 signaling cascade in promoting tumor metastasis makes TSPAN8 a novel therapeutic target for the treatment of PDAC." (PMID 34163029, 2021). "Pathway analysis revealed two TME-derived growth factors, IGF1 (log2 fold change = 6.55) and EGF (log2 fold change = 5.24) that are driving Hif1α signaling within the HCC tumor cells." (PMID 33995488, 2021). "Angiogenic growth factors, such as Vascular Endothelial Growth Factor (VEGF), Fibroblast Growth Factor (FGF), Transforming Growth Factor (TGF), and Epidermal Growth Factor (EGF), play an important role in promoting tumor angiogenesis and growth." (PMID 33803224, 2021). "EGF has been reported as a common tumor promoter in many experimental systems, such as human urothelial cells." (PMID 33926470, 2021). "At the same time, Clony stimulating factor-1 (CSF-1) produced by tumor cells can promote macrophages to secrete more EGF, which in turn can promote the production of tumor CSF-1." (PMID 33391402, 2021). "Insulin-like growth factors and epidermal growth factor are potential tumor growing effectors released by MMP’s proteolytic activities, and likely MMPs can enhance cellular proliferation." (PMID 33407452, 2021). "Given that SIRT7-modulated AKT activity, we investigated the role of SIRT7 in tumor initiation via oncogenic EGF/AKT signaling." (PMID 34433808, 2021). "Endocan enhances tumor growth driven by mutated EGFR by facilitating EGFR signaling through direct binding and enhancing the EGF-EGFR interaction." (PMID 34976811, 2021). "By contrast, the silencing of EGF in endothelial cells slows tumour growth and decreases the proportion of stem-like cells in xenograft models." (PMID 34831291, 2021). "Compared to control, catechin nanoemulsion at 20 μg/mL and paclitaxel at 10 μg/mL were the most effective in reducing tumor volume by 41.3% and 52.5% and tumor weight by 77.5% and 90.6% in mice, respectively, through a decrease in EGF and VEGF levels in serum." (PMID 34071530, 2021). "Consistently, expression of Snail is closely related to tumor metastasis thanks to its important role as a regulator of multitude signaling chemicals including epidermal growth factor (EGF), FGF, Wnt, Notch, TNF-α and cytokines." (PMID 34627167, 2021). "Since anchorage-independent colony growth is a hallmark of cell transformation from normal cells to cancer cells, we further examined the inhibitory activity of fargesin on anchorage-independent cell transformation induced by tumor promoters, such as EGF." (PMID 33669811, 2021). "A tumorous microenvironment with deregulated EGF signaling and tumor-like stiffness synergistically reinforce stress fiber formation and, as a consequence, leads to high actomyosin II-driven cell forces." (PMID 34440749, 2021).
tumor (continued). "The impact of age, tumor location and serum EGF on overall survival of oncological patients was investigated using a Cox regression model." (PMID 34115785, 2021). "The synergistic effect of TGF-β and epidermal growth factor (EGF) has also been shown to lead to the metastasis of tumor cells to the bone in PC." (PMID 34868907, 2021). "In tumor xenografted mice, EGF-PLGA@5Fu/PFC NPs suppressed tumor growth more effectively than 5Fu, PLGA@5Fu or PLGA@5Fu/PFC NPs." (PMID 32345258, 2020). "Amplification of platelet-derived growth factor (PDGF) and epidermal growth factor (EGF) signaling has been shown to increase tumor hyperplasia and survival." (PMID 32733369, 2020). "We further showed that the EGF/EGFR axis was critical for proliferation of tumor cells, as TAMs provided EGF to induce EGFR-positive OC cell proliferation." (PMID 32286255, 2020). "In breast cancer, they facilitate invasion of tumor cells by sustaining a signaling paracrine loop involving CSF-1 and EGF, and by the secretion of proteases." (PMID 33330508, 2020). "In both cell lines, the inhibition of the EGFR pathway was also compensated by over-expression of EGF by tumor cells only for the triple combination." (PMID 31938054, 2020). "This paracrine interaction between CSF-1-secreting tumor cells and EGF-secreting macrophages drives the migration of tumor cells and the macrophages toward blood vessels." (PMID 32182935, 2020). "Other mechanisms include the rearrangement of the tumor architecture (e.g., via MMPs), the induction of tumor cell proliferation and survival (e.g., through epidermal growth factor or IL-6), and the suppression of anti-cancer immunity (e.g., via PD-L1)." (PMID 33255584, 2020). "There have been in vivo studies of synergistic antitumor effects with chimeric toxins, that is, saporin-EGF and saponin for epidermal growth factor receptor expressing tumor xenografts." (PMID 32256588, 2020). "There was significant increased expression of EGF in tumour tissues in patients with GG genotype compared to AG genotype and AA genotype p= 0.019." (PMID 32711431, 2020). "Aberrant EGF-mediated abnormal signaling plays a vital role in increasing the ability of tumor cells to proliferate and migrate during the growth process." (PMID 32850421, 2020). "Strikingly, suppression of EGF/Spitz by RNAi expression in RasV12 clones strongly reduces invasive tumour frequency, showing that expression of this ligand sustains RasV12-driven basal extrusion in the accessory gland." (PMID 32385236, 2020). "Migratory macrophages can facilitate tumor cell movement towards blood vessels in the MMTV-PyMT model of breast cancer by forming physical contacts through an EGF/CSF1 paracrine loop." (PMID 33374595, 2020). "TAMs increase tumor cell migration and invasion through a paracrine loop which consists of macrophage-derived EGF and tumor-induced CSF-1." (PMID 32326073, 2020). "Our results suggest that long-term treatment with genistein strikingly reduced EGFR expression, and genistein contributed to the reduced reactivity of EsC cells to EGF, which amplified the anti-tumor effect of genistein in EsC cells." (PMID 32276266, 2020). "Angiogenesis and activation of the epidermal growth factor (EGFR) pathway play an essential role in tumor proliferation and metastasis." (PMID 32337094, 2020). "In response to CSF1 (secreted by tumor cells), TAMs release the epidermal growth factor (EFG) that binds its receptor on the surface of tumor cells, activating signaling of motility, matrix degradation and invasion of the surrounding tissue." (PMID 32397392, 2020). "Epidermal growth factor (EGF)/EGF receptor (EGFR) signaling is a key factor in tumor growth and the development of metastasis, and is considered a target for chemotaxis in cancer therapy." (PMID 32867284, 2020). "In contrast, LTTs that use EGF as a targeting moiety avoid the tumor cell activation pathway entirely because they ultimately use EGFR to kill the target cell." (PMID 32630411, 2020).
tumor (continued). "Total CELx HSF HER2-dependent signals (NRG1b-induced and EGF-induced) were obtained for all primary tumor samples." (PMID 32036454, 2020). "In ovarian cancer, immune cells such as M2 macrophage-like TAMs secrete EGF, which upregulates αMβ2 integrin on TAMs and ICAM-1 on tumor cells to promote association between tumor cells and TAMs." (PMID 32780245, 2020). "Epidermoid tumor cell line A431 depends on EGF signaling for proliferation and migration, which can be assessed by wound healing assays monitoring the closure of a scratch in a cell lawn." (PMID 33333826, 2020). "Immunostaining of mouse tumor spheroids isolated from ascite, confirmed that EGF was specifically detected in TAMs that were surrounded by EGFR+ tumor cells." (PMID 33194645, 2020). "The LAMC2 has an epidermal growth factor (EGF)-like domain which can be processed by MMP to interrupt the hemidesmosomes via EGFR of b4 integrin during tumor cell migration." (PMID 32467737, 2020). "EGF also has been shown to reduce E-cadherin expression and increase Vimentin expression in a variety types of tumor cells." (PMID 32376896, 2020). "ROS have been shown to induce proliferation in tumour cells and mediate the proliferation initiated by epidermal growth factor (EGF) or platelet-derived growth factor (PDGF)." (PMID 32107588, 2020). "Any decrease in EGF or CSF1 will prevent tumor growth, a situation encountered with only the triple combination." (PMID 31938054, 2020). "Evaluation of tumor volumes and weights for 20 days after injection showed that EGF-PLGA@5Fu/PFC NPs were the most effective treatment evaluated." (PMID 32345258, 2020). "Some cytokines and growth factors have been reported to increase the concentration of checkpoint ligand PD-L1 on tumor cells, such as interferon-γ (IFNγ), tumor necrosis factor α (TNFα), or epidermal growth factor (EGF)." (PMID 33233528, 2020). "The present study demonstrates that the ATF6-mediated production of EGF in SCCs induces the recruitment of vascular endothelial cells and triggers tumor angiogenesis via the activation of the EGFR signaling in vascular endothelial cells." (PMID 32630838, 2020). "EGF, which is cleared more quickly than the antibodies and is rapidly internalized, was mostly metabolized in the tumor by 24 h and localized to the cortex in the kidney." (PMID 32033318, 2020). "Tumor-associated macrophage also increases tumor angiogenesis and promotes tumor invasion and metastasis by producing proangiogenic factors such as VEGF, EGF, and MMP." (PMID 32850400, 2020). "We further confirmed that the regulation of the ATF6-mediated stimulation of the EGF pathway significantly enhanced the chemosensitivity of these tumors and delayed tumor relapse." (PMID 32630838, 2020). "In these cells, the intra-tumor levels of human/mouse EGF and EGFR varied according to the treatment." (PMID 31938054, 2020). "In neural systems, GAM-related EGF fluxes within tumor microenvironment constitute the positive feedback loop between inflammation, EGF secretion, and GBM progression." (PMID 32443749, 2020). "Another study found that ultrasound-guided PAI and anti-epidermal growth factor (EGFR) antibody conjugated to gold nanorods can effectively detect EGF-expressing primary tumour and regional lymph node metastases." (PMID 32872399, 2020). "Decorin can activate the MAPK pathway by combining with epidermal growth factor, leading to the expression of downstream p21 genes related to tumor differentiation, invasion depth, hyperplasia and metastasis, and the value of prognosis." (PMID 32786144, 2020). "In contrast, M2 macrophages express immunosuppressive cytokines and growth factors like IL-10, Arg-1, CD206, VEGF, and EGF, and can thereby promote tumor proliferation, metastasis, and angiogenesis." (PMID 32850356, 2020).
tumor (continued). "Together, these findings suggest the stimulation of tumor angiogenesis through the transcriptional upregulation of EGF expression in SCCs and the subsequent activation of the EGF-mediated signaling pathways in endothelial cells." (PMID 32630838, 2020). "Epidermal growth factor (EGF) secreted by tumor cells and corresponding immune cells cooperates with up-regulated EGFR to accelerate this process." (PMID 33511267, 2020). "EGF can directly control tumor disease and anticancer therapy by restoring the balance between prothrombotic and fibrinolytic processes." (PMID 33243184, 2020). "Panitumumab is a recombinant human monoclonal antibody that binds to EGFR, blocks the binding of EGFR ligands to cancer cells, and inhibits EGF dependent tumor cell activation." (PMID 32587771, 2020). "Collectively, these results suggest that ATF6-mediated EGF expression in SCCs is a target with which to block tumor recurrence." (PMID 32630838, 2020). "EGFR is not only expressed by tumor cells but also by endothelial cells and the EGF/EGFR pathway participates in processes of tumor vascularization." (PMID 31938054, 2020). "EGF acts as a strong mitogen for follicular thyroid cells and has been shown to increase the spheroid size in various tumor cell lines." (PMID 32033410, 2020). "EGF secreted by TAMs activates EGFR on tumor cells, which in turn upregulates VEGF signaling in surrounding tumor cells to support tumor cell proliferation and migration." (PMID 32780245, 2020). "SAH-JGZ4 not only protected against the EGF-induced expression of core pluripotency factors, but also suppressed tumor proliferation, invasion, and intrinsic oncosphere formation in A549 cells." (PMID 32694521, 2020). "EGF mRNA expression presents a bell-shaped pattern: it is significantly increased in primary tumours compared to both normal (p = 2 × 10−5) and metastatic (p = 0.0089) tissues which are expressing very similar levels of EGF (p = 0.92)." (PMID 32385236, 2020). "M2 macrophages play a major role in tumor and produce epidermal growth factor, vascular endothelial growth factor and ornithine to promote tumor cell growth, while M1 macrophages depress tumor growth by secreting IL-12 and IFN-γ." (PMID 31988807, 2020). "The researchers designed an EGFR-targeting fusion protein consisting of recombinant gelonin (rGel) toxin and EGF, and PCI of rGel-EGF was applied to EGFR expressing tumor cells in vitro and in vivo." (PMID 31936595, 2020). "We previously showed that PDCD4 protein was phosphorylated at S67, S71, and S76 via the tumor promotor EGF and TPA-mediated signaling pathways and degraded by the ubiquitin-proteasome system." (PMID 31952347, 2020). "More specifically, the tumor cells produce the colony-stimulating factor (CSF-1) leading to the attraction and growth of macrophages which in turn release epidermal growth factors (EGF) resulting in the growth and mobility increase of the tumor cells." (PMID 32221323, 2020). "In clonogenic assays, monospecific 177Lu- and 111In-trastuzumab Fab or EGF only killed tumour cells that expressed HER2 or EGFR, respectively, while the bsRICs were able to kill cells that expressed HER2 or EGFR or both receptors." (PMID 31659527, 2019). "Since EGF, bFGF, and insulin are the three main components in our sphere-formation pelletizing system, which also exist in the tumor microenvironment, we exposed MCF-7 cells to EGF, bFGF, or insulin separately." (PMID 30792382, 2019). "EGF acts as a chemotactic factor in the tumor microenvironment and promotes the motility and invasion of tumor cells, consequently accelerating metastasis." (PMID 31601953, 2019). "Previous studies utilized two-photon live-tissue microscopy to capture the effect of EGF-secreting TAMs on tumor cell phenotypes." (PMID 31817625, 2019). "When it becomes sufficiently large, the consumption of EGF at the core of the tumor will induce the dormancy of cells in this area." (PMID 31157216, 2019).